PROS1 (protein S)
Diseases named in the same sentence as PROS1 in open-access papers (continued):
Sharing a sentence is not in itself a finding about the gene and the disease.
Arthritis (8 papers, 2013 to 2024). Inflammation of a joint. "In fact, the protective role of both TAM receptor ligands Gas6 and Pros1 has already been described by our group in murine models of arthritis." (PMID 32964059, 2020). "The protective role played by Mer activation by its ligand ProS1 has been lately further confirmed in a KRN serum transfer arthritis model and in a three-dimensional model of human synovium, hence enhancing the translational value of this discovery." (PMID 32051695, 2020). "In these studies, Gas6 and Pros1 overexpression decreased arthritis severity, by reducing inflammation and by inhibiting the expression of proinflammatory cytokines." (PMID 32964059, 2020). "In a mouse model of arthritis, treatment with Gas6 or Pros1 limited inflammatory responses, consequently reducing symptoms." (PMID 31636733, 2019). "The objective of this study was to illuminate the endogenous role of the MER tyrosine kinase, and its role upon PROS1 stimulation, in two different experimental models of arthritis and a three-dimensional model of the human synovium." (PMID 29706963, 2018). "We have shown that Axl-/- and Mertk-/- mice develop more severe arthritis whereas activating these receptors by overexpressing their ligands Pros1 and Gas6 ameliorates arthritis." (PMID 30335822, 2018). "Apoptotic cell numbers and IL-16C levels were enhanced during arthritis in Mertk−/− mice and reduced in Pros1-overexpressing mice." (PMID 29706963, 2018). "Mertk−/− mice showed exacerbated arthritis pathology, whereas Pros1 overexpression diminished joint pathology in KRN STA." (PMID 29706963, 2018). "The first in vivo evidence that TAMs might be therapeutically exploited to improve arthritis was provided in CIA mice treated with adenoviruses overexpressing ProS1 or Gas6." (PMID 32051695, 2020). "Based on our results that the endogenous protective role of MER during arthritis could be further enhanced by exogenously delivered PROS1 or viral overexpression, we envision that MER targeting would be a therapeutic option to treat RA patients." (PMID 29706963, 2018). "We found that activating MER by PROS1 is indeed anti-inflammatory and also ameliorates arthritis." (PMID 29706963, 2018).
bladder cancer (8 papers, 2019 to 2025). "Three C4BP-binding aptamers also pulled down Protein S and these aptamers showed increased abundance in branched selections from late-stage bladder cancer patients." (PMID 36004048, 2022). "In MGH-U3 bladder cancer cells, which express Tyro3 alone, ProS1 was again the stronger stimulator of Tyro3 and Erk stimulation but additionally stimulated Akt phosphorylation." (PMID 31766614, 2019).
Cerebral ischemia (8 papers, 2012 to 2025). Restriction of arterial blood supply to the brain associated with insufficient oxygenation to support the metabolic requirements of the tissue. "Additionally, VZV can cause protein S deficiency resulting in transient thrombophilia which also contributes to increased risk of cerebral ischemia and can cause acute demyelination in CNS structures." (PMID 41075139, 2025). "Based on previous reports, it can be considered that the expression of protein S increases in platelets during cerebral ischemia to activate its anticoagulative and neuroprotective properties." (PMID 35268287, 2022).
Thrombocytosis (8 papers, 2012 to 2024). Increased numbers of platelets in the peripheral blood. "Among the 16 patients, five were diagnosed with APS, one was diagnosed with SLE, three had distinct protein S deficiency, one had protein C deficiency, six had anemia, five had thrombocytopenia, and two had thrombocytosis." (PMID 38822265, 2024). "Antithrombin III deficiency present in four patients, secondary thrombocytosis in three patients, protein C deficiency in three patients, protein S deficiency in one patient, and Factor V Leiden mutation in one patient were identified." (PMID 24868203, 2014). "Urinary loss of antithrombin III, protein C, and protein S, which normally have an anticoagulatory action, is coupled with increased production of fibrinogen and coagulation factors, thrombocytosis, and platelet hyperaggregability." (PMID 23346271, 2012).
thrombotic disease (8 papers, 2004 to 2025). The formation of a blood clot in the lumen of a vessel or heart chamber; causes include coagulation disorders and vascular endothelial injury. "We describe a novel variant, c.1871‐14T>G, in intron 14 of PROS1 gene identified in two patients with PS deficiency from two unrelated families with a history of thrombotic disease." (PMID 29225857, 2017). "We suggest that protein S deficiency should be considered in the cases of some patients with unexplained retinal vascular occlusions, particularly when occurring in young patients or when there is a positive family history of thrombotic disease." (PMID 15448814, 2004). "Recognition of an association of protein S with thrombotic disease may suggest specific therapeutic approaches." (PMID 15448814, 2004). "Thrombotic disorders commonly involved mutations in PROC (27%), PROS1 (12%), SERPINC1 (9%), ADAMTS13 (5%), and JAK2 (3%)." (PMID 40488813, 2025). "In this report, we describe a novel c.1871‐14T>G variant in PROS1 intron 14, identified in two patients from two unrelated families, both with PSD and history of thrombotic disease." (PMID 29225857, 2017). "In conclusion, the present case highlights the possible relationship between psychiatric and thrombotic disorders, suggesting that both the MTHFR mutation and protein S deficiency could lead to psychotic disorders." (PMID 40700101, 2025).
AIDS (7 papers, 2006 to 2024). A syndrome resulting from the acquired deficiency of cellular immunity caused by the human immunodeficiency virus (HIV). "Opportunistic infections render HIV and AIDS patients susceptible to a hypercoaguable state, including lower protein S levels." (PMID 26245588, 2015).
Arterial thrombosis (7 papers, 2010 to 2025). The formation of a blood clot inside an artery. "Our patient presented with arterial thrombosis of the cerebrovascular system as the initial presentation of protein S deficiency." (PMID 40084314, 2025). "An association was found between low levels of protein C, protein S and AT and arterial thrombosis, but only elevated fibrinogen levels, smoking, positive family history and hyperlipidemia showed statistical significance." (PMID 24346777, 2013). "C. W. Kim and J. W. Kim reported a case of celiac artery thrombosis, and splenic infarction was surgically treated, and it was related to protein S deficiency." (PMID 23304160, 2012). "Utterly, the lifetime risk of arterial thrombosis was 2–fold higher in subjects with any deficiency (i.e., protein S, protein C, or antithrombin) compared to non#x2013;deficient subjects." (PMID 21254740, 2010). "In a case–control study, arterial thrombosis was recorded more frequently in 88 cases with protein S, protein C, or antithrombin deficiency (19% arterial thrombosis) compared with control subjects with venous thromboembolism without these deficiencies (1% arterial thrombosis)." (PMID 21254740, 2010). "Protein C deficiency, protein S deficiency, Factor V mutation, prothrombotic polymorphisms, Factor II G2021A, and the homozygous TT genotype of the methylenetetrahydrofolate reductase (MTHFR) C677T polymorphism were found to be associated with increased risk of arterial thrombosis in neonates." (PMID 36313901, 2022).
Autoimmunity (7 papers, 2011 to 2025). The occurrence of an immune reaction against the organism's own cells or tissues. "The post-infectious etiology is likely secondary to autoimmunity and is usually seen 7-10 days after an acute infection, although anti-Protein C and Protein S antibodies are rarely detected." (PMID 40530218, 2025). "Dysregulation of the PROS1-MERTK signaling pathway has been implicated in a spectrum of diseases, including autoimmune disorders, chronic inflammatory conditions, and several types of cancer." (PMID 39535659, 2025). "In physiological conditions, the interaction between PROS1 and MERTK is essential for efferocytosis—the clearance of apoptotic cells by phagocytes—which is critical for maintaining tissue homeostasis and preventing chronic inflammation and autoimmunity." (PMID 39535659, 2025).
chronic kidney disease (7 papers, 2019 to 2024). Impairment of the renal function secondary to chronic kidney damage persisting for three or more months. "With respect to coexistence of HIT and protein S deficiency, there is a single report of extensive skin ulcer showing microthrombi in a patient with end stage renal disease." (PMID 39533629, 2024). "The higher prevalence of AT, protein S, and protein C deficiencies in hemodialysis patients might be explained by increased inhibitor consumption owing to a state of increased coagulation activity resulting from chronic kidney disease (CKD) and dialysis." (PMID 31539375, 2019).
epilepsy (7 papers, 2011 to 2024). A brain disorder characterized by episodes of abnormally increased neuronal discharge resulting in transient episodes of sensory or motor neurological dysfunction, or psychic dysfunction. "miR-19b, is an experimentally validated regulator of genes implicated in phagocytosis signaling (e.g. Pros1, Tub), a microglial function significantly altered in epilepsy." (PMID 30114263, 2018).
ischemia (7 papers, 2013 to 2020). A hypoperfusion of the BLOOD through an organ or tissue caused by a PATHOLOGIC CONSTRICTION or obstruction of its BLOOD VESSELS, or an absence of BLOOD CIRCULATION. "However, MK-4 activate protein S that was found to significantly reduce total brain water content and improved and treated post-ischemia cerebral blood flow." (PMID 32150581, 2020).
liver cirrhosis (7 papers, 2016 to 2025). "Low plasma levels of antithrombin, protein C, and protein S by advanced liver cirrhosis were found to be associated with PVT development, but reduced portal vein flow velocity was the only variable independently associated with PVT development." (PMID 30105510, 2019). "Certain predisposing factors such as liver cirrhosis, pregnancy, myeloproliferative neoplasms, Factor V Leiden mutation, protein C or protein S deficiency, and the JAK2V617F mutation may coexist with the NEN in some NEN patients, further increasing susceptibility to thrombosis." (PMID 39857994, 2025). "Similar to the prothrombin-antithrombin balance, we reckon with the possibility that the decrease of the factor V is compensated for by the decrease of the delimiting factors protein C and protein S. This is supported by the finding of thrombomodulin resistance in liver cirrhosis patients." (PMID 28472132, 2017). "However, it appears likely that our data also reflect unequal kinetics of the changes of coagulation factors and natural anticoagulants during the course of liver cirrhosis, as for example the activity of protein S appears to be largely unaffected even in patients with end stage liver disease." (PMID 27171213, 2016).
myeloproliferative diseases (7 papers, 2013 to 2025). "Major causal factors include myeloproliferative neoplasm (MPN), factor V Leiden (FVL) mutation, prothrombin G20210A gene mutation, antiphospholipid antibodies, hyperhomocysteinemia, paroxysmal nocturnal hemoglobinuria, antithrombin (AT), protein C (PC), protein S (PS) deficiencies, and others." (PMID 27335832, 2013).
oral squamous cell carcinoma (7 papers, 2009 to 2025). "Here we identify PROS1 as a mediator of Oral Squamous Cell Carcinoma (OSCC) in proliferation, cell survival and migration." (PMID 28118606, 2017).
papillary thyroid cancer (7 papers, 2020 to 2025). "Abnormal expression of Protein S (PROS1) affects human papillary thyroid cancer progression, especially associated with lymph node metastasis." (PMID 36276977, 2022). "The previous study also suggested that PROS1/TAM receptors were the effector of metastasis in the progress of papillary thyroid cancer progression." (PMID 36685506, 2022). "This study explores the role of AXL and its ligand PROS1 in the generation and biological behaviour of papillary thyroid cancer (PTC)." (PMID 36203174, 2022). "In this study, the expression levels of AXL/PROS1 were elevated in human papillary thyroid carcinoma." (PMID 36203174, 2022). "Having identified AXL as a tyrosine kinase family with similar attributes, we aimed to explore the PROS1-AXL-mediated TAM signaling pathway for the clinical management and prognosis of papillary thyroid cancer by providing a deeper understanding of its underlying molecular mechanisms." (PMID 36203174, 2022).
pneumonia (7 papers, 2012 to 2023). An acute, acute and chronic, or chronic inflammation focally or diffusely affecting the lung parenchyma, caused by an infection in one or both of the lungs (by bacteria, viruses, fungi, or mycoplasma.). "Taking these data together, we propose a mechanism of pneumonia-induced vitamin K depletion, leading to a decrease in activated MGP and protein S, aggravating pulmonary damage and coagulopathy, respectively." (PMID 33023681, 2021).
thyroid cancer (7 papers, 2014 to 2025). "We statistically analyzed the relationships between recurrence risk, BRAF gene mutation, gender, age at first thyroid cancer diagnosis, tumor size, extrathyroidal invasion, lymph node metastasis, and distant metastasis as well as the expression levels of PROS1, CLU, and LRG1." (PMID 40797389, 2025). "Correlation between PROS1 protein expression and clinicopathological parameters of thyroid cancer patients." (PMID 40797389, 2025). "PROS1 from CAFs and tumor cells facilitated the migration and invasion of thyroid cancer cells expressing MERTK, emphasizing the significance of the PROS1/MERTK signaling pathway in PTC progression both in vitro and in vivo." (PMID 40433916, 2025). "Three downregulated proteins (protein S [PROS1], clusterin [CLU], and leucine-rich α-2-glycoprotein 1 [LRG1]) were found to be significantly associated with poor overall survival in thyroid cancer using differential analysis and Kaplan–Meier survival analysis." (PMID 40797389, 2025). "The PROS1 and FN1 others 12 genes alternations were identified as important diagnostic biomarkers for thyroid cancer through the meta-analysis the gene expression profiling of clinical thyroid nodules." (PMID 32164602, 2020). "Conditional media from CAFs overexpressing PROS1 significantly upregulated the expression of β‐catenin, C‐myc, CCND1, and p‐SMAD2 in thyroid cancer cells." (PMID 40433916, 2025). "The candidate NRGs were all highly expressed in thyroid cancer tissues, and candidate neoantigen genes, such as CDH6, ODZ1, and PROS1, were significantly differentially expressed in thyroid cancers." (PMID 37854594, 2023). "Additionally, poorly differentiated thyroid carcinoma and PTC tumor cells at stage IV (AJCC 8th) PTC typically expressed low to moderate levels of PROS1, CLU, and LRG1." (PMID 40797389, 2025).
atrial fibrillation (6 papers, 2011 to 2025). A disorder characterized by an electrocardiographic finding of a supraventricular arrhythmia characterized by the replacement of consistent P waves by rapid oscillations or fibrillatory waves that vary in size, shape and timing and are accompanied by an irregular ventricular response. "Antivitamin K oral anticoagulants (AKOA) function by reducing plasma concentrations of the vitamin-K-dependent proteins (FII, FVII, FIX, FX, protein C, and protein S) and are crucial in the pharmacological treatment of cardiac and thromboembolic disorders, as well as atrial fibrillation." (PMID 33572412, 2021).
Cognitive impairment (6 papers, 2012 to 2025). Abnormal cognition is characterized by deficits in thinking, reasoning, or remembering. "Protein S is shown to be associated with neuronal protection against ischemic injury, suggesting its beneficial role for cognitive impairment due to vascular dementia." (PMID 35174198, 2021). "Given that serum PROS1 levels reflect AD pathogenesis in 5XFAD mice, we compared the abundance of PROS1 in serum between cognitively normal (CN), mild cognitive impairment (MCI), and AD dementia groups via western blot analysis." (PMID 31727875, 2019).
Hepatic steatosis (6 papers, 2016 to 2025). Steatosis is a term used to denote lipid accumulation within hepatocytes. "They demonstrated that fatty liver is significantly positively associated with protein C, protein S, fibrinogen, and factor VIII and negatively associated with antithrombin III and aPTT." (PMID 37386502, 2023). "When the models were stratified according to glucose tolerance status, the same results were found in all categories, namely, an increased protein S level in the intermediate status and in hepatic steatosis." (PMID 37386502, 2023). "According to their interpretation, a fatty liver leads to an increased synthesis of proteins C and S in the liver, with protein S being a coproduct of protein C. As natural anticoagulants, they inhibit the coagulation cascade, which would counteract a prothrombotic state promoted by fatty liver." (PMID 37386502, 2023).
Insulin resistance (6 papers, 2012 to 2024). Increased resistance towards insulin, that is, diminished effectiveness of insulin in reducing blood glucose levels. "In this study, insulin resistance (HOMA-IR) correlated with Antithrombin III, heparin cofactor 2, P-selectin, fibronectin, vitamin K dependent protein S and alpha 2 antiplasmin." (PMID 33674695, 2021).
osteoporosis (6 papers, 2016 to 2025). A condition of reduced bone mass, with decreased cortical thickness and a decrease in the number and size of the trabeculae of cancellous bone (but normal chemical composition), resulting in increased fracture incidence. "Recently, a single-nucleotide polymorphism (SNP) associated with the PROS1 gene was attributed to an etiological role in osteoporosis." (PMID 38203403, 2023). "Furthermore, the SNP rs8178616 mapped to the PROS1 gene was found to be correlated with SHBG and eBMD, giving rise to the hypothesis that PROS1 may play a role in the pathogenesis of osteoporosis." (PMID 38203403, 2023).
Parkinson disease (6 papers, 2017 to 2022). A progressive degenerative disorder of the central nervous system characterized by loss of dopamine producing neurons in the substantia nigra and the presence of Lewy bodies in the substantia nigra and locus coeruleus. "Nonetheless, all the evidence suggests that PROS1, PPBP, and LCN2 are known to be well detectable in vivo in blood and thus represents a potentially valuable source of biomarkers for Parkinson’s diseases." (PMID 36189230, 2022). "Receiver operating characteristic (ROC) of PPBP, PROS1, and LCN2 for prediction of Parkinson’s disease and healthy controls." (PMID 36189230, 2022).
Purpura Fulminans (6 papers, 2012 to 2025). A severe, rapidly fatal reaction occurring most commonly in children following an infectious illness. "Homozygous mutations of PROS1, encoding vitamin K-dependent protein S (PS), have been reported so far to be associated with purpura fulminans, a characteristic fatal venous thromboembolic disorder." (PMID 32489947, 2019). "FFP 15–20 ml/kg given 8–12 hourly may be used as first line therapy to treat acquired neonatal purpura fulminans in association with protein C or protein S deficiency while the underlying cause is being investigated." (PMID 38388746, 2024). "Furthermore, homozygous congenital deficiency of either protein S or protein C causes neonatal purpura fulminans; a combined disseminated intravascular coagulation and haemorrhagic disease that often presents with skin necrosis." (PMID 26181660, 2015). "Lethal purpura fulminans develops in the very rare newborns homozygous for protein S gene." (PMID 22290807, 2012).